IL6 (interleukin 6)
Diseases named in the same sentence as IL6 in open-access papers (continued):
Sharing a sentence is not in itself a finding about the gene and the disease.
melanoma (continued). "Furthermore, a reduced secretion of IL-10 and IL-6, and of VEGF by melanoma cells has been reported within the tumor milieu." (PMID 29285320, 2017). "Considering the pro-metastatic role of both WNT5A and IL-6 in melanoma progression, a combined treatment that effectively inhibits the presently demonstrated WNT5A-IL-6 positive feedback loop is an attractive strategy to successfully impair melanoma cell invasion and metastasis." (PMID 27191257, 2016). "Next, we selected three melanoma cell lines—WM852, HTB63 and A375—that are phenotypically classified as invasive by the HOPP algorithm, and compared their levels of WNT5A and IL-6 mRNA/protein expression." (PMID 27191257, 2016). "Thus, we studied the pro-inflammatory pathway activity by measuring the expression of TNF-α inducible genes IL1-α, IL1-β, IL6 and IL8 across melanoma cell lines pairs." (PMID 27175588, 2016). "Two recent studies have demonstrated a link between IL-6 secretion and WNT5A expression in melanoma cells, suggesting that the combined therapeutic interference with this link might be beneficial for preventing disease progression and metastatic spread." (PMID 27191257, 2016). "Moreover, it has been demonstrated that WNT5A can positively regulate the exosomal release of IL-6, and we have shown that stimulation with exogenous IL-6 can induce WNT5A expression in malignant melanoma cells." (PMID 27191257, 2016). "Our data clearly indicate that WNT5A and IL-6 co-operate to facilitate melanoma cell migration and invasion and that the combined therapeutic inhibition of both WNT5A and IL-6 signalling stands out as an effective treatment strategy to prevent melanoma dissemination." (PMID 27191257, 2016). "In support of our finding of a WNT5A-IL-6 positive feedback loop, both WNT5A and IL-6 have been reported to promote tumour cell metastasis, although the role of IL-6 has not been completely explored in melanoma." (PMID 27191257, 2016). "Combined therapeutic approaches involving anti-IL-6 Ab (for antagonizing IL-6 signaling) and Box-5 (for antagonizing WNT5A signaling) might be beneficial for treating melanoma cells." (PMID 26393652, 2015). "Studies based on transgenic mice demonstrated that mice lacking IL-6 develop fewer and smaller tumors, indicating a potential role for IL-6 in melanoma cell development." (PMID 26393652, 2015). "IL-6 and VEGF have both been shown to increase the angiogenic potential of malignant melanoma." (PMID 24766647, 2014). "Here we show, that malignant melanoma cell lines treated with recombinant (r)WNT5A induces a prominent, immediate release of immunomodulatory and pro-angiogenic factors IL-6, IL-8, VEGF and MMP2, while transcriptional activation of these genes remained unaffected." (PMID 24766647, 2014). "The B1 receptor stimulation decreases melanoma cell migration and decreases tumor growth, proliferation, vascularization and immune cell infiltration, while increasing the expression of the pro-inflammatory and anti-tumor cytokines IFN-γ and IL-6." (PMID 23691222, 2013). "Our results demonstrate that CCL2 and IL6, which are present in the SSMC, also promote an activation of STAT3 and that STAT3 silencing prevents the acquisition of the mesenchymal, stemness and melanoma-initiating phenotypes." (PMID 24344100, 2013). "Accordingly, SOID-8 inhibited IL-6-induced activation of STAT3 and JAK2 in melanoma cells." (PMID 23166634, 2012). "Lipopolysaccharides can stimulate normal human melanocytes to produce IL-1β, TNFα, IL-6, IL-8, CCL2, CCl3, and CCL5, and chemotherapy of melanoma-bearing mice results in enhanced expression of CCL5 and the CXCR3 ligands CXCL9, CXCL10, and CXCl11 by tumor cells." (PMID 22745913, 2012). "Our results revealed that the pro-angiogenic, AA-derived eicosanoids PGE2, 12-HETE, and 15-HETE, as well as the key inflammatory factors interleukin-6 (IL-6) and tumor necrosis factor α (TNF-α), were dramatically reduced in B16 melanoma and LLC tumors treated with D6D-RNAi or SC-26196." (PMID 23112819, 2012).
melanoma (continued). "Finally, there was a dramatic increase of TNF-α and IL-6 following co-culture of CTL with DC and lysates from H-1PV-infected melanoma cells." (PMID 22029859, 2011). "Over 80% of the human melanoma cell lines expressed TGF-β, IL-8, IL-6, VEGF, PDGF-AA and OPN." (PMID 24281094, 2010). "Therefore, one of our objectives was to investigate the potential relationship established between IL-6 and/or TNF-α and the white-blood-cell-based inflammatory indices, which could provide valuable information about the efficacy of melanoma treatment." (PMID 40564098, 2025). "14,15-EET induces G-CSF/IL-6 production in vivo, enhancing STAT3 activation in neutrophils to promote MMP-9 expression and suppress TRAIL expression, with neutrophil-derived MMP-9 being essential for inducing angiogenesis in dormant micrometastases in melanoma." (PMID 40564191, 2025). "With ongoing clinical trials on the combination of ICI and tocilizumab for malignant melanoma, urothelial carcinoma, and non-small cell lung cancer (NCT04940299), further studies are needed to clarify the optimal timing, dosing, and integration of IL-6 blockade in ICI-based regimens." (PMID 41244903, 2025). "Additionally, the exploration of targeted therapies, focusing on IL-6 and CTLA4, as well as investigating the immune microenvironment in HCV-infected melanoma patients, could lay a solid foundation for future therapeutic strategies." (PMID 39336572, 2024). "Compared to the control, silencing IL-6 shows smaller tumor weight, reduced UPC1 expression in scWAT, and rescued CAC phenotype in colon cancer model; blocking IL-6 by anti-IL-6 antibody results in a reduction of body fat and UPC protein level in scWAT of melanoma mice model." (PMID 39125923, 2024). "Therefore, apart from the regulation by NF-κB downstream of IRE1α, the expression and secretion of IL-6 and TNF-α might also be directly transcriptionally regulated by XBP1 downstream of IRE1α in melanoma undergoing ER stress." (PMID 38291473, 2024). "Melanoma exosomes have been shown to induce a spectrum of macrophage phenotypes secreting a variety of anti-inflammatory (IL-4, IL-10, IL-11, and IL-13) but also pro-inflammatory (TNF-α, IL-12B, IL-1β, IL-6, iNOS, and CCL22) factors, reflecting the spectrum of phenotypes detected in the TME." (PMID 38533720, 2024). "Two models were obtained to predict metastasis (including “all patients” or only patients “at early stages of melanoma”), and a series of attributes were seen to predict the progression of metastasis: Breslow thickness, infiltrating BCL-2 expressing lymphocytes, and IL-4 and IL-6 serum levels." (PMID 37046835, 2023). "We suggest that the combination of elevated frequency and high immunosuppressive activity of circulating MDSC and increased IL-6 and IL-8 concentrations in plasma could be considered as promising prognostic biomarkers of resistance to ICI in advanced melanoma patients." (PMID 36860876, 2023). "Similarly to what was previously reported for luteolin, another flavanone from citrus fruits, hesperidin (its aglycone form is called hesperetin), inhibited the progression of melanoma in tumor-bearing mice by activating CD8+ T cells and promoting IL-6 secretion by activating the PI3K-AKT pathway." (PMID 36768978, 2023). "IL6 activates the antitumor immunity, regulates the secretion of the anti-inflammatory cytokine IL10 in the melanoma cells via the PI3K and ERK related pathways, and promotes the E/P-selectin- and ICAM-1-dependent extravasation of the cytotoxic T cells in melanoma lesions in vivo." (PMID 35327461, 2022). "Thus, the downregulation of IL6, IL10, IL12, sICAM-1, sICAM-3, sPECAM-1, and CD40L secretion may lead to the melanoma progression and impair survival of the patients with metastatic melanoma." (PMID 35327461, 2022).
melanoma (continued). "Other studies have shown that – rather than decrease the availability of local IL-6 – exercise in rodents resulted in an increase to IL-6 gene expression within B16 melanoma tumours following voluntary wheel running, and this was accompanied by a 60% reduction to tumour growth." (PMID 35359426, 2022). "B vitamins affect the increased level of TNF-α and IL-6 in the tumor microenvironment, the activation of NF-κB factor in macrophages and the increased abundance of Bacteroides, Faecalibacterium and Prevotella, which stimulate the response to immunotherapy in NSCLC and melanoma patients." (PMID 36428677, 2022). "Furthermore, the negative predictive value of baseline plasma IL-6 expression in response to immunotherapy has been previously reported in patients with melanoma and pancreatic cancer." (PMID 35550592, 2022). "Moreover, MAFs generate an immunosuppressed melanoma TM by multiple mechanisms, such as increasing the expression of various inflammatory and immunosuppressive factors; among others, TGF-ß, IL-6, MMPs, PGE2, COX-2, CXCL5, and PDL1/2, which dramatically impair the anti-tumor activity of immune cells." (PMID 34440462, 2021). "Notably, miR-146a upregulation with concomitant increased COX2, PDL1, VEGFA, CCL2, IL6, IL8 and MCL1 expression characterized the MDSCs induced in vitro by melanoma extracellular vesicles from monocytes from healthy donors, suggesting cell type-specific regulation of the miR-146a/COX2 axis." (PMID 32967672, 2020). "WNT5A modulates melanoma cell behavior via multiple cell surface receptors/co-receptors, including ROR2 and Frizzleds, and downstream molecular targets, such as APT1, IL-6, and PKC-STAT3, which in turn affect various melanoma cell functions, including migration and invasion." (PMID 32033033, 2020). "In addition, among the genes indirectly regulated by miR-146a through NFkB activity, we found CCL2, IL6, and VEGFA, which contribute to the proinflammatory phenotype, CD274 (PDL1), which promotes melanoma cell proliferation, and BCL2L1 and MCL1 antiapoptotic genes." (PMID 32967672, 2020). "Nevertheless, S100B as well as IL-6 might not represent the most sensitive and most useful serum or blood markers for the detection of tolerance breakage in melanoma." (PMID 32188047, 2020). "Moreover, BRAFV600+ melanoma cell lines secrete immunosuppressive cytokines such as interleukin 10 (IL-10), vascular endothelial growth factor (VEGF), and interleukin 6 (IL-6), which promote the recruitment of regulatory T cells and myeloid-derived suppressor cells." (PMID 32731406, 2020). "Based on our present finding that IL‐6 and WNT5A independently mediate their effects on the invasive migration of BRAFi‐R melanoma cells, we investigated whether and how elevated IL‐6 secretion and WNT5A expression translated into increased BRAFi‐R melanoma cell migration and invasion." (PMID 30582770, 2019). "However, in contrast to this latter finding, we found that the IL‐6/WNT5A positive feedback loop is absent in BRAFi‐R melanoma cells." (PMID 30582770, 2019). "The second requirement, the immunosuppressive activity of melanoma-derived extracellular vesicles, was demonstrated by down-regulation of MHC molecules and co-stimulatory receptors on monocytes and DCs, induced production of IL-6, and reduced T cell proliferation in MLRs." (PMID 31269655, 2019). "However, we did not observe a significant reduction in Rac1‐GTPase activity in HTB63‐R cells treated with the combination of IL‐6 Ab and Box5, arguing against an essential role of Rac1 in the IL‐6‐ and WNT5A‐dependent invasive migration of BRAFi‐R melanoma cells." (PMID 30582770, 2019). "However, the secretion, signalling and role of IL‐6 have, to the best of our knowledge, not yet been studied in acquired BRAFi‐R melanomas." (PMID 30582770, 2019). "However, we found that IL-6 induced growth inhibition in melanoma cells (unpublished data) and was therefore deemed an unlikely candidate." (PMID 28450382, 2017).
melanoma (continued). "Since B16 melanoma cells do not produce IL-6 (and not shown), IL-6 may be from tumor inflammatory environments not from B16 melanoma cells." (PMID 29340089, 2017). "However, we found only a poor correlation (Pearson correlation = 0.194) between WNT5A and IL-6 mRNA expression (data not shown) in the invasive melanoma cell lines." (PMID 27191257, 2016). "For instance, melanoma cells released pro-angiogenic factor IL-6, vascular endothelial growth factor (VEGF) and MMP2, in a Wnt5a-dependent manner, and co-culture of Wnt5a-silenced melanoma cells with ECs showed decreased EC branching, compared with control melanoma cells." (PMID 27608847, 2016). "In addition, gene expression of IL-6, MDR-1, and MMP-9 in the picked-up B16F1 spheroids was used to evaluate the effect of spatial relationship to endothelial cells (HUVEC) on the invasive capacity of melanoma cells." (PMID 25058006, 2014). "We also found that inhibition of MAPK signaling pathway in human melanoma cells by genetic depletion of mutant BRAF or specific inhibitors reduced production of multiple immunosuppressive cytokines such as IL-6, IL-10, and VEGF, in most cases without affecting cell viability." (PMID 23755373, 2013). "Importantly, the pro-tumorigenic effects of SSMC or of IL6 were completely abrogated when cells were knocked down for STAT3, thereby demonstrating the key role of STAT3 activation in the acquisition of the tumorigenic potential by melanoma cells." (PMID 24344100, 2013). "Another study on the 1286 melanoma cell line showed high SOCS-3 expression, the natural inhibitor of JAK/SAT3 signalling, and that forced suppression of SOCS-3 could render the cells again responsive to inhibitory effects of OSM or IL-6." (PMID 24381786, 2013). "However, specific data on whether tazarotene directly inhibits IL-6 production in the melanoma tumor microenvironment are still lacking." (PMID 40699636, 2025). "Additionally, Il-6 and tumour necrosis factor β (TNF-β) synthesized by skin adipocytes induce a paracrine differentiation of melanoma cells, expressed by reduced melanogenesis and promotion of cultured melanoma cells proliferation, by the repression of miR-211 expression." (PMID 35334544, 2022). "Furthermore, fibroblasts activated by melanoma cells showed upregulation of the MMPs’ expression mediators’ levels (pERK, p-p38, CD44, RUNX), enhanced secretion of lactate, several cytokines (IL8, IL6, CXCL1, CCL2, ICAM1), and proteins related to angiogenesis (GM-CSF, DPPIV, VEGFA, PIGF)." (PMID 35538545, 2022). "However, no such reductions were observed after IL-6 knockdown in BRAFi-R2 melanoma cells." (PMID 36551563, 2022). "Therefore, monocytes from melanoma progressively acquire a CD14+/HLA-DR-/low suppressive phenotype that alters T-cell proliferation and interferon-γ production while enhancing the secretion of inhibitory cytokines such as IL-6, TNF-α and TGF-β within the tumor milieu." (PMID 29755693, 2018). "Although IL-6 serum levels were not statistically different between nevi and melanoma patients in our cohort, this preliminary in vitro assay suggests that besides the known HLA-G role, in melanoma, it may influence immune cells in the tumor microenvironment to produce this cytokine." (PMID 41268555, 2025). "As previously introduced, during melanoma development, IFN-γ and IL-6 drive IDO-1 overexpression through a negative and positive feedback mechanism, respectively." (PMID 39062529, 2024). "Utilizing melanoma and NSCLC cell lines we show that CD1c+CD14+ cells emerge from cDC2s but not monocytes, through IL-6 and macrophage colony-stimulating factor (M-CSF/CSF1) secreted by tumor cells." (PMID 38242119, 2024). "The decreased level of these modifications in melanoma cells may be the reason for the lack of silencing of pro-inflammatory pathways, which is also evidenced by the increased level of pro-inflammatory cytokines (IL-6/12 and ANGPTL 3) compared to untreated cells." (PMID 39682683, 2024).
melanoma (continued). "Of note, we have also tested the levels of other cytokines (i.e. IL6, TNF-α and IL1β) in THP-1 cells exposed to CM coming from melanoma cells and we have not observed any significant modulation." (PMID 36418472, 2023). "We found that IL-6, IL-8, TNF-α and CCL5 were significantly increased in the plasma of metastatic and non-metastatic melanoma patients as compared to HD." (PMID 36860876, 2023). "In conclusion, we provide evidence of an additive negative effect of IL-6, HGF, and MCP-2 on clinical response to single or combination ICI in advanced melanoma." (PMID 36007304, 2022). "Surprisingly, neither WNT5A nor IL-6 contributed to the increases in MARCKS expression and activity in BRAFi-R melanoma cells, unlike in BRAFi-sensitive melanoma cells." (PMID 36551563, 2022). "Whilst we did not examine how melanoma cells stimulate osteoblasts to produce more RANKL, previous studies of other cancers such as prostate and breast have identified IL6 and PTHrP as RANKL stimulation factors." (PMID 31323160, 2020). "Rb9 did not modify the melanoma lysate response in relation to IL-12, TNF, and IL-10 secretion but significantly reduced IL-6." (PMID 32010152, 2019). "Despite the absence of an IL‐6/WNT5A loop, we found that both an IL‐6 blocking antibody and the WNT5A antagonist Box5 alone impaired the elevated invasive migration of BRAFi‐R melanoma cells, but combined use of the two was more effective." (PMID 30582770, 2019). "Another group showed that VEGF, IL-6 and MMP-2 proteins were present in the culture supernatants of human melanoma cells with no direct evidence of VEGF detection in their derived exosomes." (PMID 27760548, 2016). "The inflammation status in B16 melanoma and LLC tumors with and without D6D inhibition was determined by measuring gene expression of the inflammatory cytokines IL-6 and TNF-alpha." (PMID 23112819, 2012). "The expression of MAF in antitumor CD8+ T cells contributes to their polarization toward a depleted phenotype, and TGF-β and IL-6 are able to induce MAF expression in CD8+ T cells in vitro and in vivo, while tumor-specific CD8+ T cells lacking MAF tend to eliminate melanoma cells." (PMID 37762054, 2023). "We also evaluated the protein amount of a set of 12 cytokines and chemokines, including IL-2, IL-4, IL-5, IL-6, IL-10, IL-12, IL-17A, TNF-α, IFN-γ, MCP-1, MIP-1α, and eotaxin in TIF and plasma samples of C57BL6 mice, engrafted or not engrafted with B16 melanoma cells." (PMID 34604232, 2021). "Moreover, in the human melanoma cell line A375, CHOP raises the IL-6 production without binding to its promoter but trapping protein(s) such as liver-enriched inhibitory protein, an isoform of NF-IL6, which would otherwise inhibit IL-6 transcription." (PMID 28066415, 2016). "Since there was about 11-fold reduction in IFN-γ release while only 3-fold reduction in IL-6 secretion were observed, this indicated that a lack of IFN-γ production may be the major defect in PBMC from melanoma patients in response to HD IL-2." (PMID 27153543, 2016). "In particular, the cytokine interleukin-6 (IL-6), which is secreted by C918 but not present in OCM-1A, plays diverse and important roles in cancer cell migration, cancer progression, and epithelial-to-mesenchymal transition and can be triggered after human melanoma cell–endothelial interactions." (PMID 34249699, 2021). "In our study, recombinant IL-6 inhibited the proliferation of B16F10 cells, though use of R848 to up-regulate IL-6 expression may not be appropriate for the treatment of patients with a malignant melanoma." (PMID 30042824, 2018). "Interestingly, we found that only IL-6 and IL-8 expression increased significantly after ATF3 deletion, which could also explain why the ATF3 knockout HDFs did not have a significant effect on melanoma cell growth and migration." (PMID 32373541, 2020).